CD4 (CD4 molecule)
Diseases named in the same sentence as CD4 in open-access papers (continued):
Sharing a sentence is not in itself a finding about the gene and the disease.
cancer (continued). "Factors such as age, latest CD4 cell count, latest HIV viral load, and transmission route were found to be associated with SARS-CoV-2 infection, while age, cancer, latest CD4 cell count, and latest HIV viral load were associated with SARS-CoV-2 hospitalization." (PMID 38630534, 2024). "High-risk group was highly scored in release of cancer cell antigen (step 1), while low-risk group highly scored in cancer cell antigen expression (step 2), CD4 T cell recruiting (step 4), Treg cell recruiting (step 4) and recognition of cancer cells by T cells (step 6)." (PMID 37653101, 2023). "It was found that the expression of NALCN was significantly associated with CD8+ T cells infiltration level among 14 cancer types, CD4+ T cells among 17 cancer types, neutrophil among 16 cancer types, DCs among 19 cancer types, macrophages among 19 cancer types, and B cells among 5 cancer types." (PMID 37152978, 2023). "We reasoned that the relative homogeneity observed within each individual but also between patients in TILs-CD4+ samples may be associated to cancer-related expansions." (PMID 37600765, 2023). "Methionine consumption by cancer cells causes defects in the methionine cycle in CD4 T cells." (PMID 37147330, 2023). "Then, the TIMER2.0 database was applied to explore the potential relationship between the SPEN expression and infiltration level of immune cells, including natural killer T cells (NKT), CD4 + T cells, cancer-associated fibroblast (CAF) and regulatory T cells (Tregs)." (PMID 37620924, 2023). "In one of the studies, Shaw et al14 reported that the presence of cancer and advanced stage caused a relative decrease in CD4 T lymphocyte activity compared to the healthy control group, and this effect was reversed in those receiving androgen suppression therapy." (PMID 37877827, 2023). "We found that ADCY7 mRNA levels were strongly correlated with the infiltrating degree of CD4+ T cells, T cells gamma delta, macrophages, neutrophils, M1 macrophages, myeloid dendritic cells, mast cells, endothelial cells, cancer-association fibroblasts, and NK cells." (PMID 36979847, 2023). "Cancer development is in fact associated with macrophage reprogramming from a pro-inflammatory to an immunosuppressive phenotype accompanied by an enrichment of regulatory CD4+/FOXp3+ Tregs and exhausted CD8+-T-lymphocytes." (PMID 36691794, 2023). "CD4 + T cells have been implicated in cancer immunity for their helper functions." (PMID 36827012, 2023). "Numerous studies have shown that the continuous antigenic stimulation of tumors in vivo may cause CD4+Th exhaustion and senescence, which are related to the occurrence and progression of cancer." (PMID 36925914, 2023). "Moreover, some studies showed that resting CD4 memory T cells were associated with increased overall survival in various cancers." (PMID 37664030, 2023). "Tumors with high AR expression were reported to be associated with pro-cancer regulatory T cells, and those with low AR expression were associated with anti-cancer immune cells, such as CD4, CD8, gamma delta T cells, and memory B cells in ER-positive breast cancer." (PMID 36721218, 2023). "High-affinity CD8 variants could also be introduced into primary CD4+ T cells, which have been shown to be effective vehicles in the setting of cancer immunotherapy." (PMID 37390984, 2023). "Meanwhile, data from xCell revealed that the level of CD4+ memory T cell subset infiltration was positively associated with GOLT1B expression in pan-cancer analyses, while the level of central and effector memory subset infiltration was negatively associated with GOLT1B expression." (PMID 38130634, 2023). "Moreover, GOLT1B was positively correlated with the Th2 subset of CD4+ cells and cancer-associated fibroblasts, playing a specific role in immune infiltration." (PMID 38130634, 2023). "The activated CD4 T cell is negatively correlated with the risk score and may facilitate cancer immunotherapy by improving cytotoxic T cell response." (PMID 36937439, 2023).
cancer (continued). "Accordingly, CD4:CD8 ratio has been associated with cancer risk amongst PLWH." (PMID 37476029, 2023). "The frequency of infiltrating CD4+ T lymphocytes was significantly increased in C3aR-deficient mice to mediate a more robust adaptive immune response against cancer and in light of the observation that the number of CD8+ infiltrating T cells was also higher in C3aR KO." (PMID 37296948, 2023). "An interesting multicentre meta-analysis from the previous year indicates that a reduction of the risk of cancer death among patients treated for HNSCC is significantly related to the presence of large CD4+ TILs (HR 0.77; 95% CI: 0.65–0.93) and CD8+ (HR 0.64; 95% CI: 0.47–0.88) subpopulations." (PMID 36980527, 2023). "Decreased CD4+ memory T cell size in the stroma was associated with cancer-related mortality." (PMID 38125025, 2023). "This ongoing phase II study will evaluate the clinical impact and immunological efficacy of combining a CD4‐help T‐inducer vaccine (universal cancer peptide vaccine, UCPVax) associated with atezolizumab for the treatment of locally advanced or metastatic HPV‐positive cancers (HPV16+)." (PMID 37076763, 2023). "Finally, using the TISDB database, it was found that CD276 expression was negatively associated with Act CD8 cells, Act B cells and Tem CD4 cells in most types of cancer, but positively correlated with macrophages and neutrophils." (PMID 36717836, 2023). "In the current study, we found there was a close correlation between LDHA and LDHB expression levels and multiple TIIC subsets, i.e., B cells, cancer-associated fibroblast, CD4+ T cells, CD8+ T cells, endothelial cells, and neutrophils, and massive immunoinhibitors such as VTCN1." (PMID 37547725, 2023). "Moreover, we investigated the association between the infiltration level of different CD4+ T cell subsets and clinical prognosis across different cancer types." (PMID 38130634, 2023). "Recent advances have established proof of concept in the following fields: Scientists found that a sizable fraction of non-synonymous cancer mutations were immunogenic when delivered by messenger RNA, and that CD4 + T cells were the preeminent population capable of recognizing these abnormalities." (PMID 37420174, 2023). "The expression of GSK3B was significantly inversely linked to the naive CD4+ T cells, memory B cells, NK T cells, and Tregs infiltration, and significantly positively linked to macrophage, neutrophil, cancer-associated fibroblast (CAFs), B cell plasma and activated mast cell infiltration." (PMID 36743929, 2022). "These preclinical findings translate to clinical observations, demonstrating that while personalized neoepitope-specific vaccines induce CD4+ rather than CD8+ T cell responses in cancer patients, mutation-specific CD4+ T-helper cells are capable of eradicating large tumors in cancer patients." (PMID 36303101, 2022). "Infiltration of cancer-associated fibroblasts, endothelial cells, macrophages, particularly M2 macrophages, and monocytes was more severe in high-risk patients than low-risk individuals, who exhibited high CD4+ Th1 cell infiltration in GC." (PMID 35382776, 2022). "The co-clustering of B and CD4 T cells (identified by the CD20 cluster score), which is associated with higher density of B and CD4 T cells in the IM-S region and longer survival, might negatively affect growth of cancer cells in several manners." (PMID 36077836, 2022). "In addition, CD4+ T cells, cancer-associated fibroblasts, neutrophils, T cell helper 1 (Th1) cells, and memory B cells were highly infiltrated in this group." (PMID 36408463, 2022). "Theoretically one could predict the characteristics and the specificity of each epitope (i.e. autoimmune, cancer, pathogen-related), the related bound HLA alleles, or the function of the recognized T-cells (i.e. CD4 vs CD8)." (PMID 36131910, 2022).
cancer (continued). "Furthermore, high risk score was positively related with the enrichment levels of NK cell, B cell, CD8+ T cell, CD4+ T cell, monocyte, macrophage and cancer associated fibroblast." (PMID 36467996, 2022). "Moreover, CD4+ T cells have been linked to human cancers, and they are thought to play a role in PCa growth and promotion." (PMID 35627227, 2022). "Additional mechanisms also indicate a protective role of bilirubin in cancer risk: bilirubin may act as an immuno-modulatory agent and has been shown to suppress CD4 T cell responses." (PMID 35814479, 2022). "In addition, FCGR3A expression was associated with CD8+ T cell levels in 25 cancer types, CD4+T cell levels in 28 cancer types, macrophage levels in 27 cancer types, neutrophil levels in 30 cancer types, and dendritic cell (DC) levels in 30 cancer types." (PMID 39280892, 2022). "The CD8+ and CD4+ T-cell infiltration was associated with the prognosis of cancer patients." (PMID 35578660, 2022). "Chronic inflammation coinciding with CD4+ T cell hyperactivation, on the other hand, is also associated with increased risk and mechanisms of initiation, progression, and metastatic diffusion of cancers." (PMID 35821823, 2022). "However, the RBM10 expression was positively associated with T cell CD4+ Th1 and T cell CD4+ central memory in many cancers, especially in LUAD and LUSC." (PMID 39282149, 2022). "Our preferred hypothesis is that TGFβ plays a dominant role in the conversion of CD4+ T cells to iTreg cells, because TGFβ is known to be produced in cancer tissue, is associated with an immunosuppressive state and induces the expansion of Treg cells." (PMID 35158758, 2022). "Cells positively associated with high risk scores included B cell memory, cancer-related fibroblast, class-changed memory B cell, macrophage M0, macrophage M1, NK cell activation, T cell CD4+ central memory, T cell CD4+ memory activation, T cell regulatory (Tregs), and T cell CD8+ central memory." (PMID 36212132, 2022). "In addition, a significant positive correlation was observed between the association of CD8+ T cells and CD4+T immune infiltrations with MPZL3 expression in most types of cancers based on MCPcounter algorithms." (PMID 35965540, 2022). "The result of CellMiner Cross-Database analysis showed that a higher level of CD4 mRNA expression was significantly associated with higher sensitivity of cancer cell lines to cyclophosphamide (r = 0.81, p< 0.001), cisplatin (r = 0.30, p< 0.05), and carboplatin (r = 0.47, p< 0.001)." (PMID 35433455, 2022). "In conclusion, the results of this study suggest that PDIA3 may affect the occurrence, prognosis, and treatment of a variety of cancers through its association with 11 immune cells, such as B-cell memory, plasma cells, and T-cell CD4 naive." (PMID 36046686, 2022). "Furthermore, the expression of STK38 was related to the infiltration of immune cells, such as NK cells, memory CD4+ T cells, mast cells and cancer-associated fibroblasts in a few cancers." (PMID 36232893, 2022). "In this pilot study, we identified that INHBB expression is positively correlated with the infiltration of macrophages, endothelial cells, and cancer-associated fibroblasts and is negatively associated with the infiltration of CD4+/CD8+ T cells and plasmacytoid dendritic cells." (PMID 36118865, 2022). "Interestingly, it has been confirmed that CD4+ T cells can cause cancer cell death through ferroptosis and the contact killing mechanism of anti-MHC CLASS II antibodies in vitro." (PMID 36092720, 2022). "A bubble chart created using seven different algorithms later revealed that the risk score was negatively correlated with B cells, T cell CD8+, T cell CD4+, and cancer-associated fibroblast, while positively correlated with T cell CD4+ Th1, T cell CD4+ Th2, NK cell resting, and mast cell resting." (PMID 36330457, 2022).
cancer (continued). "The present study indicates that modulating the systemic immune cell response to control an increased ratio of CD8+/CD4+ T lymphocytes could effectively counteract dietary or genetic susceptibility to cancer." (PMID 36452234, 2022). "Therefore, we explored the correlation of AATF expression levels with immune infiltration of cancer-associated fibroblasts, endothelial cells, CD4+ T cells, B cells, myeloid dendritic cells, eosinophils, and macrophages." (PMID 36275893, 2022). "Furthermore, consistent with other studies, our results showed that initiating ART at higher CD4 cell counts reduced the overall risk of developing cancer." (PMID 34873875, 2022). "T cell CD4 memory resting has a positive association with neoantigen load in many cancer types." (PMID 35534879, 2022). "Furthermore, the result in our study indicates that STK38 is negatively associated with infiltrating levels of CD4+ T cells, and it is positively correlated with NK cells and Mast cells in most cancer types." (PMID 36232893, 2022). "The lollipop chart presented that riskScore was positively correlated with Tregs, cancer-associated fibroblasts, T follicular helper cell, memory-activated CD4+ T cell, and macrophage M0 and negatively correlated with NK cell resting, mast cell activated, etc.." (PMID 35846134, 2022). "The FAM46 gene is implicated in regulating T and B cells and found negatively associated with naïve CD4 + cells in pan-cancer GZMK encodes Ganzyme K, a serine protease closely associated with proinflammatory responses and impediment of wound-healing by inflammation and impaired epithelialization." (PMID 36267464, 2022). "Finally, HLA interactions were reduced from early to advanced disease, with loss of CD4 expression in advanced cancers." (PMID 35493454, 2022). "In addition, more recent clinical trials have shown that CD4 T cells specific against mutated neoantigens can successfully be used alone or in combination to checkpoint inhibitors to treat patients with cancer." (PMID 35903540, 2022). "Infiltration levels of cancer-associated fibroblasts (CAFs), CD4_T cells, and endothelial were significantly upregulated in the high-risk group, while infiltration levels of B cells, macrophages, and other cells were significantly upregulated in the low-risk group (all p < 0.05)." (PMID 36032681, 2022). "Therefore, PARP inhibition-mediated effect on the fine-tuned balance underlying CD4+ Th differentiation within the TME represents an additional mechanism potentially improving the outcome of cancer immunotherapy." (PMID 36428727, 2022). "Along the same lines, EPIC analyses revealed that the numbers of CD8+T cells, CD4+T cells, B cells, myeloid dendritic cells, cancer-associated fibroblasts, and hematopoietic stem cells, and immune, stromal, and microenvironment scores were higher in the low-risk group." (PMID 35769999, 2022). "The bubble plot showed that RMlnc-score was positively correlated with CD4+ T cells, cancer-associated fibroblast (CAFs), myeloid dendritic cell, macrophage M0, NK cell activated, hematopoietic stem cell while negative correlation with CD4+8 cell, monocyte, neutrophil, and B cell plasma." (PMID 35464855, 2022). "The results demonstrated that high expression of RIOK2 was associated with CD8+T cells, CD4+Th2 cells, CD4+Treg cells, and cancer-associated fibroblast infiltration in pan-cancer, whereas CD4+Th1 cells, macrophages, and natural killer cells showed the opposite association." (PMID 36518977, 2022). "And we suspected that the anti-cancer effects of PCSP-AuNPs were mediated through its immune-modulatory function since it caused an increase in CD4+/CD8+ ratio, spleen index, thymus index, and splenic lymphocyte viability, and altered the levels of immune-related cytokines in the mice." (PMID 35762637, 2022). "In addition, E. hirae and Bifidobacterium intestinihominis specific memory CD4+ T cells were associated with longer progression-free survival (PFS) in cancer patients." (PMID 34589427, 2021).
cancer (continued). "Interestingly, the co-cultivation of CD4+ T cells with cancer cells likely caused the exchange between BRM and BRG1-containing SWI/SNF CRC classes at position −255 bp." (PMID 34439305, 2021). "Our results showed that CD4+ T cells, monocytes, macrophages, cancer-associated fibroblasts, and myeloid dendritic cells were enriched in the high-risk group, which may explain why the high-risk group was related to poor prognosis." (PMID 34663340, 2021). "DMP-A was mainly presented a CD4+ immune regulator and stromal activation phenotype, associated with many related pathways, such as the cell cycle, DNA replication, Toll-like receptor, and Nod-like receptor signaling pathways in cancer." (PMID 34552879, 2021). "Our results suggest that characteristic HIV-1 integration site features — such as HIV-1 integration in RIGs, genes associated with clonal expansion of latently HIV-1–infected CD4+ T cells, and cancer-related and highly expressed genes — are found in both resting and activated CD4+ T cells." (PMID 33784259, 2021). "Wilcoxon analysis revealed that the high-risk group was associated with greater infiltration of cancer-associated fibroblasts, follicular helper T cells, CD4 + T cells, M0 macrophages and M1 macrophages, while the low-risk group was correlated with greater infiltration of B cells and M2 macrophages." (PMID 34238114, 2021). "Moreover, the proportion of CD4+ T cells was statistically significantly positively associated with CRC-specific survival in patients with stage III cancers." (PMID 34204621, 2021). "In our study, advance cancer stage was negatively associated with levels of B cells, CD4+ T cells, naïve CD4+/CD4+, naïve CD4+ T cells, CD4+CD28+ T cells, CD8+CD28+ T cells and positively associated with NK cells, WBC counts, monocytes, neutrophils, eosinophils, basophils, MLR, NLR, ELR, BLR, PLR." (PMID 34488711, 2021). "In addition, XDH expression was associated with infiltrating levels of CD4+ T cells in 9 cancer types, B cells in 12 cancer types, CD8+ T cells in 16 cancer types, DCs in 22 cancer types, macrophages in 9 cancer types, and neutrophils in 19 cancer types." (PMID 34496841, 2021). "In addition, the frequency of peripheral blood CD4+ TSCM decreased significantly in patients with CRC, demonstrating that cancer can cause an imbalance in the proportion of circulating CD4+ T cell subsets." (PMID 34327142, 2021). "CBX4 showed significant negative correlations with infiltrating B cells (p < 0.05) and CD4+ T cells (p < 0.01), and positive correlations with myeloid derived suppressor cells (MDSCs) (p < 0.05) and cancer associated fibroblast (CAFs) (p < 0.001), as well as a low immunoscore." (PMID 34222240, 2021). "However, it has also been reported that infiltration of CD4+Foxp3+ T-cells is associated with a favorable prognosis in some types of cancers." (PMID 34647108, 2021). "However, some other immune cells, such as M0 macrophages, CD4 + T cells, and cancer associated fibroblasts, were positively related to the risk scores of patients with LUAD." (PMID 34408216, 2021). "The risk of cancer waned to insignificance by 5 years for the advanced CD4 nadir category." (PMID 33803641, 2021). "In addition to CD8+ CD28null cells, CD4+ CD28null T-cells also expand in cancer patients and are associated with poor prognosis." (PMID 34680058, 2021). "The results showed that DPP4 expression significantly correlated with infiltration of CD8+ T cells, CD4+ T cells, Treg, B cells, NK cells, dendritic cells, neutrophils, macrophages, monocytes, and cancer-associated fibroblasts in pan-cancer patients." (PMID 33614513, 2021). "The result presented that risk score was remarkably and negatively correlated with populations of resting NK cells and resting memory CD4 + T cells, whereas positively related with infiltration of cancer associated fibroblast, M2 macrophage, and T regulatory cells (Tregs)." (PMID 34589117, 2021).